IL17A (interleukin 17A)
Diseases named in the same sentence as IL17A in open-access papers (continued):
Sharing a sentence is not in itself a finding about the gene and the disease.
asthma (continued). "Thus the addition of CXCL-1, IFN-γ, IL-5, IL-17A, EGF, eotaxin, IL-lβ, IL-4, IL-12p40, IL-13, and MDC serum concentrations to blood eosinophils and neutrophils adds significant value to the definition of the Difficult-to-Control asthma endotype." (PMID 28686637, 2017). "However, Lunding and colleagues showed in murine experiments that exacerbation of experimental asthma depends on IL-17A which is produced by NK and not Th17 cells." (PMID 27468754, 2016). "The transient increase of lung IL-17A could be mediated through transient circulating levels of adipose-tissue-originated IL-1β and IL-23, suggesting a WAT-lung axis in “metabolic programming” of asthma in adulthood." (PMID 27087690, 2016). "Our data demonstrated that reinfected mice showed an increased production of IL-17A, IL-6, TNF-α, IL-4 and IL-5, suggesting a pattern of mixed Th2/Th17 responsiveness, which was previously observed in studies with helminths and also allergic disorders, such as rhinitis and asthma." (PMID 26814713, 2016). "This study highlights an important interaction between IL-17A and TLR3 signaling in excessive airway inflammation, and control of IL-17A/TLR3-mediated NF-κB/IRF3 activation may be a novel therapeutic target to prevent exacerbation of asthma." (PMID 26418032, 2015). "Indeed, high concentrations of dexamethasone further significantly increased IL-17A production by cells from the patients with SR asthma, a phenomenon not observed in cells from the patients with SS asthma." (PMID 25772594, 2015). "Interestingly, patients with severe asthma are found to have higher levels of the pro-inflammatory cytokine IL-17A in sputum and BAL, and the severity of airway hypersensitivity correlates with airway neutrophilia and levels of IL-17A expression." (PMID 26557245, 2014). "Any data in anti-IL-17A trials for asthma are not available so far." (PMID 24032029, 2013). "The effect of Budesonide and Formoterol was tested “in vitro” on IL-17A, RORγ(t) and FOXP3 expression in cultured T-lymphocytes from mild-moderate asthma/persistent rhinitis patients, and on nasal and bronchial epithelial cells stimulated with NW and Ss from mild-moderate asthma/persistent rhinitis." (PMID 23573194, 2013). "Taken together, the production of IL-17A may not simply suppress Th2 responses, but also enhance them to promote a severe phenotype of asthma in certain situations." (PMID 24454477, 2013). "In order to study whether different subgroups of asthma patients could have differences in the expression of sputum IL-17A or IL-8 mRNA levels, we compared allergic to non-allergic asthmatics and mild to moderate/severe asthmatics." (PMID 17083726, 2006). "However, whether and how SIRT6 regulates IL-17A pathogenicity in severe asthma has not been deciphered." (PMID 38135684, 2023). "Further examination of protein targets that were identified to be suppressed in response to the combined activity of IL-17A/F and TNF-α could provide valuable mechanistic data for delineating molecular processes related to the pathophysiology of neutrophilic airway inflammation and severe asthma." (PMID 36517803, 2022). "We found that IL-17A mRNA expression was not decreased in the asthma group compared to controls in moDCs co-cultivated with epithelium (p = 0.285), but revealed a significantly lower IL-17A mRNA expression in moDCs alone from asthma (p = 0.005) and COPD (p = 0.049) patients compared to controls." (PMID 32842623, 2020). "As it has been shown that IL-17A and IL-17C both require IL-17RA for the induction of inflammatory mediators in target cells and IL-17C promotes Th17 cell responses we hypothesized that the specific IL-17C receptor IL-17RE has a function in OVA-induced experimental asthma." (PMID 32641167, 2020). "In the current study, the inflammatory cytokines, IL17A, IL33, and IFNγ, were elevated in serum of patients with both allergic and nonallergic asthma, reflecting an active inflammatory state in all our asthmatic patients." (PMID 30306094, 2018).
asthma (continued). "Because IL-17A is associated with increased numbers of neutrophils in adults with asthma, levels of GRO were measured in BAL fluid as well as in PBEC culture supernatants following IL-17A and IL-22 stimulation, with or without budesonide." (PMID 27746241, 2017). "It is of note that although the chosen PAH have been shown to enhance allergen-induced experimental asthma, only DEP-PAH and BaP modulated IL-17A and IL-22 production, showing that not all AhR ligands behave similarly." (PMID 25860963, 2015). "The observation that IL-17A, neutrophils, and the Th17 response do not contribute to AHR in our asthma model clearly contrasts with that observed from a model in which adoptive transfer of in vitro polarized Th17 OTII T-cells is followed by antigen challenge." (PMID 24069338, 2013). "As IL-17A and IL-17F cell frequency was very low in the OVA-asthma mice (data not shown), we were not able to detect alteration of Th17 cell frequency after cell therapy." (PMID 22792275, 2012). "Treatment of established asthma with rapamycin, however, did not significantly alter the HDM-induced increases in lung mRNA levels of IL-4, IL-13 and IL-17A." (PMID 22685525, 2012). "While IL-17A does not appear to be specifically correlated with either RSV- or RV-bronchiolitis, IL-17A may contribute to airway hyperresponsiveness seen in asthma." (PMID 38410509, 2024). "However, two clinical trials of humanized anti-IL-17A monoclonal antibodies, secukinumab and CJM112 failed to improve asthmatic symptoms in severe asthma patient." (PMID 38131042, 2023). "We found that STAT3 phosphorylation as well as the expression of IL-6 and IL-17A could not be reversed by Dex treatment, which indicates their involvement in corticosteroid resistance of OVA- and ozone-induced asthma." (PMID 34760922, 2021). "We tested this hypothesis by comparing plasma cytokines, including IL-2, IL-5, IL-10, IL-13, IL-17A, IL-22, IL-33, IFN-γ, and TNF-α and the adipokine, leptin in normal weight and overweight/obese children, both with and without asthma in a cross-sectional study." (PMID 39902293, 2024). "Brodalumab, a humanized mAb that binds to IL-17RA, thereby blocking the receptor and the downstream signal pathways of IL-17A, IL-17F, and other IL-17 isoforms, also did not achieve improvement in patients who were taking ICS and had inadequately controlled moderate-to-severe asthma." (PMID 39194521, 2024). "Furthermore, IL-17A, but not IL-17F, enhances airway smooth muscle contraction, migration, and proliferation, which facilitates airway hyperresponsiveness (AHR) and airway remodeling, key characteristics of asthma." (PMID 36078171, 2022). "Moreover, IL-17A/F was under detectable level in the BALFs of OVA/OVA–IL-18 Tg and WT mice, suggesting that Th17 cells may not play a role in our mouse asthma model." (PMID 23382928, 2013).
Arthritis (676 papers, 2005 to 2026). Inflammation of a joint. "Medium-dose triptolide not only significantly reduced arthritis scores and levels of IL-6 and IL-17A, but also caused substantially less ovarian damage (E2, estrous cycles) compared to the high-dose group." (PMID 40918529, 2025). "In the presence of IL-6, nTregs exhibit reduced stability and are prone to differentiate into Th17 cells, which secrete IL-17 a cytokine closely associated with joint inflammation in arthritis." (PMID 39629263, 2024). "Disease-Gene Network analysis revealed that IL-17A-related changes in gene expression in these cells are associated with experimental arthritis, knee arthritis, and musculoskeletal disease gene-sets." (PMID 34054865, 2021). "Previous studies have demonstrated a pathologic role for IL-17A in mouse models of arthritis by neutralizing this cytokine or using IL-17A deficient mice." (PMID 34040613, 2021). "In a model of collagen-induced arthritis it was described that WT CD4+ T cells secrete more IL-17A when cultured with IL-10 deficient B cells." (PMID 31249364, 2019). "Recently, a treatment comprising IL-1β in combination with IL-17A reportedly enhanced the expression of genes associated with arthritis and cell migration in a monolayer culture of the human synovial sarcoma cell line." (PMID 31614911, 2019). "Reduced circulating and lymph nodes CD4+IL-10+ T cells have been reported in subjects at risk for RA, with a subsequent increase in peripheral CD4+IL-17A+ T cells in close relationship with the onset of the arthritis." (PMID 31295951, 2019). "When we crossed IL-1 cTg with either IL-6-, IL-17A/F-deficient or Stat3 conditional knockout mice, we observed significant inhibition of arthritis development." (PMID 30361689, 2018). "The other enriched pathways like “Role of IL-17A in Arthritis” with –log (p-value) 1.64 also validated the association of σB in arthritis." (PMID 29731966, 2018). "Here, we focused on IL-17A-induced molecular effectors from experimental systems including those implicated in juvenile and adult arthritis." (PMID 30127787, 2018). "First, we aimed to determine if a putative role of IL-17A in the generation of pain is linked to a pathogenic role in arthritis." (PMID 28871176, 2017). "Other previous studies on IL-17A has provided much evidence of Th17 cytokine as a pathogenic effector in RA and experimental arthritis." (PMID 29182672, 2017). "IL-17A, a major cytokine involved in arthritis, upregulates CXCL1, which is known to cause increased cell migration, angiogenesis, and activation of the STAT-3 pathway." (PMID 27102666, 2016). "In contrast, IL-17 deficiency mitigates arthritis development, as seen in mice that lack IL-17A or those treated with anti-IL-17-blocking antibodies; IL-17 overexpression exacerbates disease progression and induces a chronic, erosive form of the disease." (PMID 26284069, 2015). "IL-17A-deficient mice were resistant to arthritis while elevated IL-17 expression induced arthritis." (PMID 22229105, 2012). "Furthermore, the presence of this polymorphism in arthritis and patients resistant to antituberculosis drugs generates an increase in serum levels of IL‐17A, as observed by Correa in serum and gingival tissue." (PMID 39887950, 2025). "In addition, Collinsella has been linked to cause severe arthritis in mouse models by promoting the expression of IL-17A and thereby increasing gut permeability." (PMID 39749132, 2024). "The number of patients with extended arthritis was low, but it remains of interest to further study if the IL-17A rs8193036 polymorphism in oligoarthritis patients could serve to predict the risk of disease extension." (PMID 39125893, 2024). "However, CIA mice, a widely used autoimmune arthritis model, do not suffer from SpA, and self-resolution occurs around 60 days after immunization; IL-17A has a major impact on arthritis, but arthritis occurs when IL-17A is deficient." (PMID 37893130, 2023).
Arthritis (continued). "Secukinumab, a human monoclonal antibody that binds to IL-17A, is already used clinically to treat arthritis-associated symptoms and joint disease damage in ankylosing spondylitis and psoriatic arthritis, further supporting the antagonistic role of IL-17A in joint disease." (PMID 33671471, 2021). "Disease-gene network analysis showed that IL-17A-induced changes in chondrocytes and synovial fibroblasts are associated with experimental arthritis, knee osteoarthritis, and musculoskeletal disease, which further highlights the potential importance of this cytokine in OA." (PMID 34054865, 2021). "Anti-IL-17A antibodies ameliorate the severity of arthritis, cartilage damage, and bone loss." (PMID 33613566, 2020). "Adoptive transfer of MDSCs to RA mice ameliorated the disease symptoms (delayed onset of arthritis, reduced arthritis scores, and reduced joint inflammation and damage) and caused a concomitant decrease in IL-17A gene expression and accumulation of Th17 cells in the spleens." (PMID 27007054, 2016). "K/BxN serum transfer arthritis was induced in IL-17A-deficient and wild-type mice." (PMID 27165410, 2016). "A recent study confirmed that the combined blockade of TNFα and IL-17A is more effective in inhibiting cytokine, chemokine, and matrix enzyme responses from human mesenchymal cells and in blocking tissue destruction associated with a mouse model of arthritis." (PMID 25904914, 2015). "Mice that received combined treatment of cromolyn and anti-IL-17A showed minor wight loss and significantly reduced clinical severity of arthritis relative to mice that only received anti-IL-17A treatment, suggesting that mast cell blockade may potentiate the biological therapy." (PMID 38168103, 2024). "Since the severity of K/BxN serum-induced arthritis in their IL-17R deficient mice is similar to that in our IL-17A KO mice, IL-17A may have the dominant role in the IL-17 family members for arthritis induction, although possible important role of IL-17F cannot be excluded." (PMID 23671588, 2013). "In this study we showed that the IL-23/IL-17A immune pathway is critical for the progression of arthritis into a chronic destructive synovitis in a non-autoimmune arthritis model, which is in line with the critical pathogenic role for IL-17A in the arthritis process." (PMID 20017902, 2009). "In a collagen-induced arthritis mouse model, both compounds alleviated arthritis symptoms, decreased serum levels of anti-type II collagen immunoglobulin G and interleukin-17A, and downregulated T helper 17-specific genes in the spleen." (PMID 41797973, 2026). "In CIA mice, triptolide changed serum E2 and FSH levels, the estrous cycle, arthritis scores, IL-6, and IL-17A levels." (PMID 40918529, 2025). "We also determined the concentrations of the cytokines IL-6, IL-10, IFNγ, TNFα, IL-17A, IL-17F, and IL-22 in serum samples of the arthritis patients." (PMID 40806470, 2025). "A total of 6 mg/kg/d for 22 days improved foot-plantar swelling and arthritis scores in RA rats and regulated the balance of pro-inflammatory factors, such as IL-1β, IL-6, and IL-17A, and anti-inflammatory factors, such as IL-4 and IL-10." (PMID 40864815, 2025). "Therapeutic effects were assessed via arthritis index, paw swelling, and serum cytokines (IL-1β, IL-6, IL-17A)." (PMID 40864815, 2025). "In PsA models, IL-17A inhibition effectively prevents arthritis development, consistent with clinical responses observed in PsA therapeutics." (PMID 41583484, 2025). "In terms of dosage courses, a 9-week triptolide course was the most effective in suppressing arthritis scores; however, lengthier courses showed a tendency for IL-17A to rebound." (PMID 40918529, 2025). "IL-17A released from T helper 17 cells plays an important role in autoimmune responses, increasing inflammation and damage in joint bones and promoting arthritis." (PMID 40128226, 2025).
Arthritis (continued). "Treatment with an anti-IL-23 antibody was also effective in both the prevention and treatment phases of arthritis, indicating the essential role of the IL-23/IL-17A axis in this disease model." (PMID 39379604, 2024). "Although there are fewer studies on IL-17A and angiogenesis after stroke, the role of IL-17A on angiogenesis in diabetes mellitus and inflammatory diseases such as arthritis and allergic pulmonary has been demonstrated." (PMID 37884768, 2024). "In the present study, levels of the representative pro-inflammatory Th1/Th17 cytokines (Il-1b, Tnf-a, Il-6, and Il-17a) in a CIA arthritis model were increased by CIA and reversed by CpdA in an Ffa4 gene-dependent manner." (PMID 38892051, 2024). "IL-17A plays a proinflammatory role in several immune disorders, and IL-17A-blocking antibodies can effectively alleviate several diseases, including arthritis." (PMID 38791080, 2024). "GMSC‐Exo demonstrated comparable or higher efficacy compared with GMSCs in suppressing the expression of IL‐17A and increasing the expression of IL‐10, thereby reducing the incidence of arthritis and bone erosion." (PMID 38712483, 2024). "The IL17A peptide-based vaccine with alum adjuvant successfully induced antibody production and suppressed the arthritis score and joint thickness." (PMID 36737108, 2023). "A recent meta-analysis showed similar effectiveness of anti-IL-17A agents and TNFi in the treatment of arthritis, with superior cutaneous responses to anti-IL-17A agents." (PMID 37511421, 2023). "The functional enrichment analysis of 132 unique DCEGs in the purple module derived from AECs dataset enriched in key biological functions such as IL-13 Signaling, role of IL-17A in arthritis, glutamate removal from folates, histamine biosynthesis." (PMID 37438356, 2023). "Ten of the pathways of interest in arthritis were selected, highlighting the Ifng, Tnf, Jun, Il17a, Kdr, and Cxcl5 genes as having the most significant interaction and relevance." (PMID 36730179, 2023). "The IL17A antibody titre was assessed using ELISA, and arthritis score and joint thickness were monitored two times a week." (PMID 36737108, 2023). "To test the effect of the IL17A vaccine on SpA, we evaluated the arthritis score and joint thickness of rats administered IL17A or KLH-control vaccine every few days after MT injection." (PMID 36737108, 2023). "Secukinumab is a monoclonal antibody targeting IL-17A that was found to result in rapid improvement of arthritis, dactylitis and enthesitis in children with ERA and JPsA." (PMID 35961761, 2023). "Although findings from studies on various murine models of arthritis have suggested IL-17A to be essential for both inflammation and bone destruction, inhibitors of IL-17A did not have sufficient effect compared to other biological agents." (PMID 36982247, 2023). "This suggests that IL-17A is dispensable for the enhanced arthritis observed in sPLA2-IIA–expressing mice using the K/B×N serum-transfer model." (PMID 35076027, 2022). "In monocytes and synoviocytes obtained from arthritis rats, the IL-17A-mediated migration and target gene expression was alleviated by cyanidin." (PMID 36012322, 2022). "In the CIA model, the neutralization of IL-17A coincident with arthritis development or in mice with established arthritis reduced joint swelling by inhibiting the onset and progression." (PMID 36296709, 2022). "The results show that GMSC‐Exo has the same or stronger effects compared with GMSC in inhibiting IL‐17A and promoting IL‐10, reducing incidences and bone erosion of arthritis, via inhibiting IL‐17RA‐Act1‐TRAF6‐NF‐κB signal pathway." (PMID 34953015, 2022). "We have also demonstrated that treatment with anti-IL-17A monotherapy resulted in the significant reduction in severity of arthritis and axial inflammation." (PMID 35055042, 2022).